PTH (parathyroid hormone)
Diseases named in the same sentence as PTH in open-access papers (continued):
Sharing a sentence is not in itself a finding about the gene and the disease.
Hypercalcemia (continued). "The most common histological etiology was parathyroid adenoma, and typical biochemical characteristics were found as follows: elevated PTH, hypercalcemia, and normal vitamin D levels." (PMID 40351902, 2025). "Clinically, the patient presented with hypocalciuria, hypercalcemia, normal or mildly elevated PTH levels, hypokalemia, hypomagnesemia, hypophosphatemia, normal blood pressure, chondrocalcinosis (CC), and diabetes mellitus." (PMID 40070587, 2025). "In situations with unsuppressed PTH secretion like a parathyroid adenoma, this mechanism becomes detrimental, leading to enhanced calcium reabsorption and maintaining hypercalcemia." (PMID 40362670, 2025). "The clinical manifestations of PHPT, resulting from chronic hypersecretion of PTH and ensuing hypercalcemia, primarily affect bones and kidneys." (PMID 40709121, 2025). "This study revealed that combining Mg with calcitriol treatment can reduce hypercalcemia and similarly suppress PTH while protecting, at least in part, the vasculature from calcium and phosphate deposition." (PMID 40008355, 2025). "The most common etiologies of PTH-independent hypercalcemia include sarcoidosis and tuberculous Mycobacterial disease." (PMID 40284609, 2025). "An 82-year-old female with stage 4 chronic kidney disease (CKD) presented with asymptomatic hypercalcemia and elevated parathyroid hormone (PTH) levels." (PMID 41210046, 2025). "Of the 10 cats that had documentation of hypercalcemia, 7/10 cats were medically managed for idiopathic hypercalcemia (based on PTH profile), given medications to try and minimize calciuria, or both." (PMID 40011049, 2025). "Hypercalcemia was followed by a reduction in TransCon PTH dose, a reduction of active vitamin D, or a decrease in supplemental calcium or calcium on demand." (PMID 40709359, 2025). "It results from excessive secretion of parathyroid hormone (PTH), leading to hypercalcemia, which can cause a range of symptoms including fatigue, muscle weakness, neuropsychiatric disturbances, and nephrolithiasis." (PMID 40109792, 2025). "This is seen in our small cohort as well, in which 70% of the patients had marked elevated PTH levels and 50% had significant hypercalcemia." (PMID 40142758, 2025). "Chronic granulomas increase the conversion of calcifediol to calcitriol, leading to enhanced intestinal calcium absorption, bone resorption, hypercalcemia, hypercalciuria, and suppression of PTH levels." (PMID 40531748, 2025). "We present a rare case of postpartum hypercalcemia in a lactating woman with suppressed endogenous parathyroid hormone (PTH), in whom ectopic PTH or PTHrP secretion was suspected after exclusion of common causes." (PMID 41487858, 2025). "This condition affects up to 2% of postmenopausal women and is marked by hypercalcemia paired with elevated or inadequately suppressed levels of parathyroid hormone, primarily due to a solitary parathyroid adenoma in 85-90% of cases." (PMID 40342440, 2025). "He presented with hypercalcemia, hypophosphatemia, suppressed intact parathyroid hormone, low serum alkaline phosphatase, an eGFR of 72 mL/min/1.73 m2, and hypercalciuria." (PMID 40428323, 2025). "Due to persistent hypercalcemia observed in previous laboratory tests, parathyroid hormone (PTH) levels were measured." (PMID 40182382, 2025). "Laboratory workup revealed severe hypercalcemia (ionized calcium: 1.81 mmol/L) with normal renal function and significantly elevated parathyroid hormone (PTH) levels." (PMID 40062143, 2025). "Hypercalciuria is often driven by hypercalcemia, which is tightly regulated by parathyroid hormone, and calcitriol." (PMID 40529990, 2025). "Primary hyperparathyroidism (PHPT) is a common endocrine disorder characterized by hypercalcemia resulting from autonomous parathyroid hormone (PTH) secretion." (PMID 41036141, 2025).
Hypercalcemia (continued). "FHH1 is characterized by lifelong stable mild hypercalcemia, inappropriately normal/high PTH levels, normal or low-normal phosphate levels, and low urinary calcium excretion." (PMID 40177730, 2025). "A peculiar aspect of our case is the presentation of hypercalcemia and suppressed PTH, which also contributed to the initial suspicion of sarcoidosis." (PMID 40431192, 2025). "Laboratory evaluation revealed hypercalcemia (ionized calcium 1.49 mmol/L; total plasma calcium unadjusted for albumin 2.81 mmol/L, 11.4 mg/dl), suppressed PTH (<1 pmol/L) and reduced 1,25-dihydroxyvitamin D (<12 pmol/L)." (PMID 40547129, 2025). "Along with elevated levels of PTH and ALP, the hallmark abnormalities of PHPT include hypercalcemia, hypophosphatemia, and hypercalciuria." (PMID 40539180, 2025). "Other etiologies of parathyroid hormone-independent hypercalcemia include exogenous vitamin D intoxication, medication adverse effects, endocrinopathies, immobility, and, less commonly, granulomatous diseases." (PMID 41024908, 2025). "On further review, she reported three recent hospital visits for similar concerns with labs concerning for moderate hypercalcemia (maximum Ca2+ of 13.3 mg/dL; reference range, 8.5-10.5 mg/dL) with an appropriately suppressed parathyroid hormone (PTH) level." (PMID 41024908, 2025). "In 2004, a patient was diagnosed with LCNEC following blood test findings of hypercalcemia and elevated PTH levels." (PMID 41464736, 2025). "Elevated PTH levels, in conjunction with hypercalcemia and imaging findings, support the diagnosis of TPTH." (PMID 41301699, 2025). "Primary hyperparathyroidism (pHPT) is an endocrine disorder characterized by the overproduction of parathyroid hormone (PTH) leading to hypercalcemia." (PMID 40807089, 2025). "Parathyroidectomy normalizes serum calcium and PTH levels, alleviating hypercalcemia-related symptoms." (PMID 41018270, 2025). "Primary hyperparathyroidism (PHPT) is characterized by excessive secretion of parathyroid hormone (PTH), leading to hypercalcemia and various systemic manifestations." (PMID 41347015, 2025). "Clinicians should recognise that lithium alone can provoke clinically significant hypercalcaemia, even when PTH levels are normal." (PMID 41185877, 2025). "The patient's preoperative laboratory tests indicated hypercalcemia, with a serum calcium level of 14.2 mg/dL (SI: 3.55 mmol/L), along with an elevated PTH levels and low 25(OH)D levels, findings confirming PHPT." (PMID 40822048, 2025). "Initially, she presented with asymptomatic hypercalcemia and elevated PTH levels, indicating primary hyperparathyroidism." (PMID 41210046, 2025). "The initial use of the hormonal form of vitamin D, 1,25(OH)2D or calcitriol, to suppress PTH was hampered by the frequent side effects of the hypercalcemia and hyperphosphatemia resulting from the development of parathyroid resistance to calcitriol." (PMID 41515987, 2025). "Subsequently, serum PTH levels were measured for the differential diagnosis between hypercalcemia of malignancy and severe primary hyperparathyroidism." (PMID 39831932, 2025). "Markedly elevated serum 25-hydroxyvitamin D concentrations above 150 ng/ml (≈375 nmol/L), together with severe hypercalcaemia, hypercalcuria, and suppressed or undetectable parathyroid hormone levels, are hallmarks of vitamin D toxicity." (PMID 41362524, 2025). "Simultaneous hypercalcemia and elevated PTH levels (or inappropriately normal levels) represent the most important factors to diagnosticate PHPT." (PMID 40149663, 2025). "Second, serum Li concentrations were significantly higher in the hyper i-PTH group than those in the normal i-PTH group and in the hypercalcemia group than those in the normocalcemia group." (PMID 40747083, 2025).
Hypercalcemia (continued). "There are biochemical findings that are suggestive of adynamic bone disease: low levels of PTH, low bone-specific alkaline phosphatase, hypercalcemia, and vascular calcification, with the golden standard for diagnosis remaining bone biopsy." (PMID 41301699, 2025). "Primary hyperparathyroidism (pHPT) is a common endocrine disorder that results in the overproduction of parathyroid hormone (PTH) and subsequent hypercalcemia." (PMID 40637883, 2025). "It underscores the importance of considering systemic sarcoidosis as a potential etiology in cases of acute PTH-independent hypercalcemia resistant to initial therapy." (PMID 39906901, 2025). "Laboratory tests revealed hypercalcemia, hypophosphatemia, and elevated parathyroid hormone (PTH) levels, consistent with SHPT." (PMID 39997653, 2025). "Primary hyperparathyroidism (PHPT) is a relatively common endocrine disorder characterized by excessive secretion of PTH, leading to dysregulation of calcium homeostasis with hypercalcemia." (PMID 39876875, 2025). "Ten patients with higher rhPTH1-84 doses at baseline (82.8 ± 33 μg/day) had hypocalcemia; 14 patients with lower doses at baseline presented with calcium values indicating hypercalcemia and lower TransCon PTH doses after 1 month." (PMID 40709359, 2025). "Combined analytical, imaging, and histological findings supported a diagnosis of PHPT due to excessive PTH secretion, presenting with symptomatic hypercalcemia and multiple brown tumors, a presentation that raised early concern for PC." (PMID 41293386, 2025). "This manifests as persistent hyperphosphatemia, hypercalcemia or hypocalcemia, thereby stimulating the parathyroid gland to secrete parathyroid hormone (PTH)." (PMID 40510469, 2025). "It is important to note that the definitive diagnosis of pHPT is confirmed by the presence of hypercalcemia along with a simultaneous elevation of PTH." (PMID 40860575, 2025). "At the renal level, CASR is thought to play a crucial physiological role in the defend against hypercalcaemia, promoting urinary calcium excretion independently of PTH action." (PMID 40870022, 2025). "Initial laboratory evaluation revealed hypercalcemia (corrected calcium: 2.91-3.23 mmol/L (reference range 2.2-2.6 mmol/L) with suppressed PTH at 0.7 pmol/L (reference range 1.5-6.9 pmol/L)." (PMID 41487858, 2025). "Primary hyperparathyroidism (PHPT) is the disease characterized by hypercalcemia due to autonomous production of parathyroid hormone(PTH) by one or more glands." (PMID 40822771, 2025). "Although clinical manifestations are not definitive criteria for discriminating parathyroid cancers from adenomas, severe hypercalcemia, markedly elevated PTH levels and young age can raise suspicion for parathyroid cancer." (PMID 40434298, 2025). "Hypercalcemia (OR: 1.27), often driven by the oversuppression of PTH or calcium-based phosphate binders, promotes arterial stiffness and calcific vasculopathy." (PMID 40362848, 2025). "In IH, PTH levels are typically reactively suppressed, with hypercalcemia resulting primarily from abnormalities in bone turnover." (PMID 40109792, 2025). "Her medical history was pertinent for kidney stones and preeclampsia with her first pregnancy, and PTH-independent hypercalcemia (13.8 mg/dL) approximately 1 mo postpartum while lactating 7 yr earlier." (PMID 40765620, 2025). "In 2018, mild hypercalcemia (2.63 mmol/l, NR 2.15-2.55 mmol/l), normophosphatemia (1.18 mmol/l, NR 0.81-1.45 mmol/l) with elevated parathyroid hormone level (105.9 pg/mL, NR 14.90–56.90 pg/mL), and decreased urine calcium excretion (2.45 mmol/24 h) were noted." (PMID 40357201, 2025). "The second phase involves hypercalcemia, along with elevated PTH levels, and is considered classic primary hyperparathyroidism." (PMID 40709988, 2025). "Hypercalcemia can be broadly classified into parathyroid hormone (PTH)-dependent and PTH-independent types." (PMID 41287694, 2025).
Hypercalcemia (continued). "Following renal transplantation, ongoing high levels of PTH can worsen hypercalcemia with intact kidney increasing conversion of 25OH-vitamin D to active 1,25-dihydroxyvitamin D." (PMID 40177730, 2025). "A hypercalcaemia workup, including parathyroid hormone (PTH), vitamin D, alkaline phosphatase, and a multiple myeloma screen, was conducted but did not reveal any underlying cause." (PMID 41216250, 2025). "In KTRs, calcimimetics are mainly used to manage persistent PTH autonomy with overt or persisting hypercalcemia." (PMID 41303180, 2025). "The diagnosis of PHPT is established through the detection of hypercalcemia and elevated PTH levels." (PMID 40539180, 2025). "Laboratory analyses showed an asymptomatic hypercalcemia (3.07 mmol/l) with low intact serum PTH of <6 ng/l (norm value 11–65 ng/l) while serum PTHrp was highly elevated." (PMID 39965521, 2025). "Currently, at 37 years old, she is taking 60 mg of cinacalcet and has hypercalcemia (serum calcium 11.1 mg/dL) and elevated PTH (302 pg/mL)." (PMID 40779536, 2025). "Laboratory evaluation revealed significant hypercalcemia with normal renal function and 25-hydroxyvitamin D (25[OH]D) levels, elevated PTH levels, and normal serum glucoses and thyroid function." (PMID 40822048, 2025). "The Kidney Disease Outcomes Quality Initiative guidelines recommend surgery in patients with severe hyperparathyroidism, defined as serum PTH levels >800 pg/ml accompanied by hypercalcaemia and/or hyperphosphataemia and refractory to medical treatment." (PMID 40503605, 2025). "Hypercalcemia with normal or suppressed PTH levels is classified as parathyroid-independent hypercalcemia, a condition characterized by elevated calcium levels unrelated to primary hyperparathyroidism, of which IH is one example." (PMID 40109792, 2025). "Characterized by hypercalcemia and inappropriately normal or elevated parathyroid hormone (PTH) levels, LIH can lead to skeletal complications such as osteoporosis." (PMID 40851725, 2025). "Lastly, the current study will address additional findings related to hypercalcemia, such as vitamin D levels, PTH, and treatment options." (PMID 40284609, 2025). "Firstly, the significant differences in biochemical markers, particularly extreme elevations in PTH and serum calcium, underscore the necessity of considering parathyroid carcinoma (PC) in cases with severe hyperparathyroidism and hypercalcemia." (PMID 40507262, 2025). "Diagnosis of PHP requires the presence of hypercalcaemia with an elevated or inappropriately normal PTH level." (PMID 41384172, 2025). "In case of hypercalcemia and normal serum levels of intact PTH in patients with a pNET, the serum level of PTHrp should be assessed as well." (PMID 39965521, 2025). "The patient presented with inconsistent calcium-PTH kinetics (rising calcium levels with suppressed PTH), indicating hypercalcemia driven by PTHrP." (PMID 41561737, 2025). "Severe PHPT can present as a parathyroid crisis, highlighting the importance of PTH measurement and screening for parathyroid tumors, even in cases of mild hypercalcemia." (PMID 40109792, 2025). "Biochemical evaluation revealed hypercalcemia (11.7 mg/dL), hypophosphatemia (3.9 mg/dL), and an elevated iPTH level of 76.2 pg/mL, consistent with excessive PTH secretion." (PMID 41155848, 2025). "In some cases, parathyroid hyperplasia persists even after successful renal transplantation, resulting in sustained PTH elevation and hypercalcaemia." (PMID 41301699, 2025). "The presence of moderate hypercalcemia, normal or mildly elevated serum PTH levels, hypocalciuria, and hypophosphatemia suggested the possibility of FHH." (PMID 40070587, 2025). "Incidental parathyroid carcinoma remains a well-documented phenomenon, often presenting asymptomatically or with subtle hypercalcemia and elevated parathyroid hormone (PTH) levels." (PMID 40142758, 2025).
Hypercalcemia (continued). "The mechanisms underlying the neuropsychiatric symptoms of primary hyperparathyroidism (PHPT) remain inadequately understood; nonetheless, the direct impacts of hypercalcemia and parathyroid hormone (PTH) on the central nervous system are significant." (PMID 41452859, 2025). "Even if the kidney transplantation is successful, the parathyroid function cannot return to normal, presenting hypercalcemia, hypophosphatemia, and elevated serum PTH, which is known as tertiary hyperparathyroidism (THPT)." (PMID 40510469, 2025). "PTH concentration is essential in diagnosing calcium and phosphate metabolism and is a fundamental tool for the etiological diagnosis of hypercalcemia and hypocalcemia." (PMID 40290309, 2025). "Many patients report with borderline lab results like normocalcemia with high PTH or hypercalcemia with PTH levels that are “inappropriately” within the reference range and yet still have PHPT." (PMID 40709988, 2025). "Hypercalcemia was an expected, on-target outcome in a study attempting to define a maximally tolerated dose of a PTH agonist." (PMID 39574220, 2025). "In group 1 (de novo AKI), mean PTH was appropriately suppressed (18.1 ± 9.6 pg/mL), consistent with the expected feedback inhibition by hypercalcemia." (PMID 40305356, 2025). "While hyperthyroidism can indeed accelerate bone turnover, potentially leading to elevated blood calcium levels, PTH levels in hyperthyroid-induced hypercalcemia are typically suppressed, remaining normal or low." (PMID 40224187, 2025). "Hypocalcemia triggers a rapid increase in PTH release (within minutes), while hypercalcemia activates CaSR to suppress PTH secretion and synthesis at the gene level." (PMID 41227247, 2025). "As hypercalcemia worsened due to ongoing PTH overproduction, she developed polydipsia, which resolved following treatment with elcatonin, cinacalcet, and zoledronate." (PMID 40109792, 2025). "In fact, in the presence of hypercalcemia, high levels (or inappropriately normal levels) of serum PTH are usually sufficient to diagnose hyperparathyroidism." (PMID 39851484, 2025). "The diagnosis is based on the characteristic triad of PTH, i.e., independent hypercalcemia, metabolic alkalosis, and renal insufficiency, often accompanied by normal or low serum phosphate levels." (PMID 41141160, 2025). "Even at a saturation dose for suppressing the tonic pools of PTH, aducanumab reversed aging-induced hypercalcemia to serum calcium levels only slightly higher than those in 3-month-old vehicle-treated mice." (PMID 40492090, 2025). "Three patients died <12 months while treated with an AVDA, one with hypercalcemia and two with immeasurably low PTH/hypocalcemia." (PMID 40587027, 2025). "Patients experienced a rapid decrease of hypercalcemia and hypercalciuria, with normalization of serum calcium levels, decrease of serum PTH, and stabilization of the results after 24 months of follow-up." (PMID 40177730, 2025). "Tertiary hyperparathyroidism is characterized by hypercalcemia resulting from autonomous parathyroid hormone production and usually occurs after a prolonged period of secondary hyperparathyroidism." (PMID 39839473, 2025). "The biochemical findings were consistent with severe hyperparathyroidism, characterized by markedly elevated PTH levels, hypercalcemia, and hypophosphatemia." (PMID 39997653, 2025). "The laboratory investigation revealed hypercalcemia, hypocalciuria, hypernatriuria, hypophosphaturia and normal PTH." (PMID 40417236, 2025). "Investigations revealed hypercalcaemia, suppressed PTH, chronic kidney disease, positive autoimmune serology including anti-NXP2 antibody, and imaging features consistent with calcinosis universalis." (PMID 41404451, 2025). "Patients who required prednisolone treatment generally presented with more severe clinical profiles, including marked hypercalcemia, suppressed PTH levels, and a greater burden of symptoms such as pain." (PMID 40353949, 2025).